XIAP (X-linked inhibitor of apoptosis)
Diseases named in the same sentence as XIAP in open-access papers (continued):
Sharing a sentence is not in itself a finding about the gene and the disease.
cancer (continued). "The central apoptosis-inhibitory function of XIAP and its overexpression in many different types of advanced cancers have led to significant efforts to identify therapeutics that neutralize its anti-apoptotic effect." (PMID 25120954, 2014). "In this review, we will discuss recent advances in understanding the function of IAPs in normal and malignant cells and focus on approaches to specifically neutralize XIAP in cancer cells." (PMID 25120954, 2014). "Deregulation of IAP functions aberrantly prolonging cancer cell viability, and XIAP and survivin have been recognized for their role in tumor formation and are targets for cancer therapeutics." (PMID 24173770, 2014). "Given the relevance of the NF-κB pathway in cancer, we assessed the effect of BT on phospho-NF-κB p65 and subsequent effect on NF-kB regulated proteins such as pIkBα, pbcl-2, bcl-xL, xIAP." (PMID 24495391, 2014). "The XIAP protein level correlated with the sensitivity to the anti-cancer drug cytarabine and other nucleosides." (PMID 25120954, 2014). "XIAP overexpression leads to caspase inhibition and consequently can confer resistance to chemotherapy/radiotherapy in cancer." (PMID 25574358, 2014). "As many of the cancers express elevated levels of XIAP and become refractory to apoptosis, treatment with embelin or in combination with other known anticancer drugs was found to sensitize them towards apoptosis." (PMID 24466324, 2014). "A second and even more promising approach is to sensitize cancer cells to chemotherapeutic drugs by functionally blocking XIAP via chemical compounds that bind into the BIR3 domains." (PMID 25120954, 2014). "In this context, it appears that XIAP functions as an adapter molecule necessary for cancer cell signaling." (PMID 25216527, 2014). "It has been shown that activated Akt stabilizes XIAP by S87 phosphorylation leading to survivin/XIAP complex formation, caspase inhibition and cytoprotection of cancer cells." (PMID 24581231, 2014). "Thereby, high cellular levels of XIAP interfere with “extrinsic” as well as “intrinsic” death pathways and increase the resistance of cancer cells to various pro-apoptotic stimuli." (PMID 25120954, 2014). "Our results provide significant information for understanding the increased nuclear XIAP expression in cancer cells." (PMID 25216527, 2014). "XIAP has been shown to be overexpressed in most human cancer cell lines and cancer tissues including HCC tissues." (PMID 24980821, 2014). "XIAP expression is upregulated in a variety of cancers, including breast, lung, renal and bladder carcinoma." (PMID 25328816, 2013). "It has also been shown that down-regulation of XIAP sensitizes a cancer cell to apoptosis induced by anticancer drugs." (PMID 24004568, 2013). "Utilizing the information that there is a strong interaction between XIAP and Akt in cancer, we were able to induce a synergistically potent apoptotic response after coadministration of TQ and TAM on MCF-7 and MDA-MB-231 cells." (PMID 23613836, 2013). "The majority of human cancers harbour high levels of inhibitor of apoptosis proteins (IAPs), such as the well characterised X-linked IAP (XIAP)." (PMID 23474846, 2013). "Of the IAPs, X-linked IAP (XIAP), cellular IAP-1 (cIAP1), and cIAP2, have been examined most rigorously due to their ubiquitous expression and association with cancer." (PMID 24303189, 2013). "Inhibition of XIAP by XIAP-inhibitors or Bcl-xL by using Bcl-xL-antisense oligonucleotides sensitizes cancer cells for chemotherapeutic drugs or radiation." (PMID 23474846, 2013). "Both PI-103 and 17-AAG when combined with TRAIL caused a decrease in the levels of IKKα and its phosphorylated form in TRAIL-resistant RKO cancer cells; expression of the caspase inhibitor protein XIAP was also decreased following both co-treatments." (PMID 23852390, 2013).
cancer (continued). "Previous work from our lab and others has demonstrated that Akt activation is linked to members of the inhibitor of apoptosis (IAP) family such as XIAP and survivin, which are overexpressed and dysregulated in many human cancers." (PMID 23922886, 2013). "Our findings support the use of HQS as antitumor medicine to promote apoptosis, which was inhibited by XIAP in cancer cells." (PMID 23408474, 2013). "The expression of DRs and proapoptotic (Bid, Bax, Bak, Smac/DIABLO) or antiapoptotic (FLIP, Bcl-2, Bcl-xL, Mcl-1, Akt, IAP-1, IAP-2, XIAP, survivin) proteins in cancer cells is involved in TRAIL-resistance." (PMID 23573148, 2013). "cIAP1, cIAP2 and XIAP are not only found in cancer cells, but are also broadly expressed at the mRNA level in normal cells." (PMID 23599779, 2013). "NF-κB is known to suppress apoptosis through the induction of anti-apoptotic proteins, including Bcl-2 and X-linked inhibitor of apoptosis protein (XIAP), leading to a resistance to cancer therapy and a poor prognosis." (PMID 24137468, 2013). "Reciprocally, phosphorylation of XIAP by Akt has been shown to protect XIAP from ubiquitination and degradation in cancer cells." (PMID 23613836, 2013). "We demonstrate that rapid deterministic activation of the type 1 pathway can selectively target such cancer cells, especially if XIAP is also inhibited; while inherent cell-to-cell variability would allow normal cells stay protected." (PMID 24709706, 2013). "XIAP was found to negatively regulate RhoGDI sumoylation at Lys-138 to promote cancer cell motility." (PMID 24008728, 2013). "In this study, we show that death receptor activation (such as by death ligands), along with XIAP inhibition, can lead to rapid activation of the type 1 pathway selectively in certain cancer cells." (PMID 24709706, 2013). "We further examined the potential role of other proteins, namely Mcl-1, XIAP and cIAP2 in the sensitivity of cancer cells to FL118." (PMID 23029106, 2012). "Our recent studies have proven that XIAP mediated cancer cell motilities via RhoGDI-dependent manner in regulation of cytoskeleton." (PMID 22532870, 2012). "As an inhibitor of apoptosis, XiAP over-expression is a well-described phenomenon in various types of cancer and appears to protect cells from various insults." (PMID 22276165, 2012). "XIAP, a potent endogenous inhibitor of caspase, is frequently overexpressed in many tumors and, in certain cancer type, is correlated to tumor progression." (PMID 23251610, 2012). "Our data demonstrated that overexpression of XIAP in cancer cells significantly decreased Annexin V staining, suggesting the protective role of XIAP in FL118-induced apoptosis." (PMID 23029106, 2012). "In the present study, we provided the structural basis of XIAP for its regulatory functions in cancer metastasis." (PMID 22532870, 2012). "Patients whose tumors expressed high levels of XIAP generally had a poorer prognosis than those patients whose tumors expressed low levels of XIAP in pre-chemotherapy's cancer tissue (overall survival P = 0.025, Log Rank test)." (PMID 22403616, 2012). "XIAP expression is elevated in many cancer cell lines and closely related to the progression and aggression of malignant cancer." (PMID 22532870, 2012). "Many strategies have been used to inhibit both the expression and function of XIAP and resensitize cancer cells to different cytotoxic stimuli." (PMID 23259070, 2012). "This notion was further strengthened by the experiment of Annexin V/PI staining and flow cytometry analysis after XIAP overexpression in cancer cells showing that forced expression of XIAP decreased Annexin V staining (protecting cancer cell from apoptosis)." (PMID 23029106, 2012). "The ability of XIAP to directly inhibit caspases in vivo makes it a critical element in the control of apoptotic threshold in cancer cells." (PMID 21559296, 2011).
cancer (continued). "Cancer cells frequently avert apoptosis by upregulating various prosurvival molecules such as XIAP and Hsp70, which promote cell survival by inhibiting caspase activation." (PMID 21297999, 2011). "Several key players including the Bcl-2, inhibitor-of-apoptosis (IAP) proteins XIAP and survivin, and the phosphoinositide 3-kinase (PI3K) – AKT/PKB which transmit anti-apoptotic signals in promoting cancer cell growth have been implicated in metastasis." (PMID 21559296, 2011). "Expression of XIAP protein had been detected in most of carcinoma cells, and overexpression of this protein was correlated with patients'sensitivity to anticancer drugs and prognosis." (PMID 21645409, 2011). "We have recently highlighted a new function for XIAP in cancer cells, in promoting polyubiquitination and proteasomal degradation of PTEN (phosphatase and tensin homolog deleted on chromosome ten)." (PMID 20712893, 2010). "Using XAC 1396-11 in combination with cytotoxics in vitro, evidence is presented that XIAP inhibition sensitises cancer cells to death induced by a variety of chemotherapeutic agents." (PMID 19904270, 2010). "Ultimate validation of XIAP as a cancer drug target will come from the clinical development of both the SMAC mimetics and the anti-sense based XIAP cancer therapies, both of which have recently entered Phase I clinical trials." (PMID 20067634, 2010). "XIAP-induced degradation of PTEN is thus one of the mechanisms through which cancer cells can achieve successful inactivation of PTEN tumour suppressor function." (PMID 20712893, 2010). "Recently, inhibitors of apoptosis protein (IAP) family members, e.g., c-IAP1, c-IAP2 and XIAP, were reported to act as tumor markers and were used as prognostic factors for estimating the survival of cancer patients." (PMID 20346172, 2010). "It is possible that Ras/E1A transformed MEFs are under different apoptotic pressures than the human cancer cells used in our study, resulting in XIAP having a more central role in suppressing intrinsic pathway mediated cell death." (PMID 20067634, 2010). "The inhibition or down-regulation of XIAP in cancer cells lowers the apoptotic threshold, thereby inducing cell death and/or enhancing the cytotoxic action of chemotherapeutic agents." (PMID 20618956, 2010). "If XIAP function is essential for survival of these cancer cells, then its inhibition by pharmacological or genetic targeting should increase the rate of apoptosis, without the requirement of additional exogenous signals." (PMID 20067634, 2010). "Elevated XIAP protein expression is described in a number of human cancers, including lymphoma, colon, lung, renal, hepatocellular, and prostate cells." (PMID 20618956, 2010). "Multiple studies in EOC and other cancers have identified XIAP suppression to be a key mechanism in chemotherapy resistance." (PMID 19603033, 2009). "It has been reported that constitutively active NF-κB signaling leads to TRAIL-resistance by upregulating XIAP in multiple human cancer cells, and in certain tumor cell types, NF-κB is the primary cause for TRAIL resistance." (PMID 19895686, 2009). "The translation of XIAP is stimulated under different conditions of cellular stress and overexpression of XIAP can be an important event in cancer progression and resistance to treatment." (PMID 18283311, 2008). "Antisense oligonucleotides directed against XIAP sensitise cancer cells to chemotherapeutic drugs in vitro and those developed by Aegera Therapeutics Inc. are currently being evaluated in phase I and II clinical trials." (PMID 18283311, 2008). "A decrease in the levels of XIAP has been reported to sensitise cancer cells to cytotoxic T lymphocytes, radiation, and anticancer drugs." (PMID 18283311, 2008). "Accordingly, other IAPs overexpressed in cancers, such as XIAP or survivin, are considered as potential therapeutic targets, despite they are also expressed in normal tissues." (PMID 17968430, 2007).
cancer (continued). "Considerable evidence has now accrued through application of a broad range of technologies to a wide spectrum of in vitro and in vivo model systems to substantiate XIAP as a valid molecular target in cancer therapeutics." (PMID 16804528, 2006). "Likewise, XIAP is also increased in the residual cancer tissues of preclinical mice models that received IMWA treatment." (PMID 39917292, 2025). "XIAP is highly expressed in various chemoresistant cancer cells." (PMID 40078400, 2025). "Targeting these domains, hLf may enhance the apoptotic response, particularly in cancer cells where XIAP is often overexpressed." (PMID 40076649, 2025). "However, it should be noted that not all eight members have been clearly and fully elucidated in terms of their enzymatic/interactive functions in cancer cells, except XIAP, c-IAP1/2, survivin, and BRUCE, which will be discussed briefly below." (PMID 40223934, 2025). "This could enhance Bcl-2 degradation and apoptosis, particularly in resistant cancer cells where XIAP and Bcl-2 are overexpressed." (PMID 40841912, 2025). "This specificity underscores the role of XIAP in conferring cancer resistance." (PMID 40486906, 2025). "The results indicated that XIAP protein was increased in the residual cancer tissue." (PMID 39917292, 2025). "Additionally, there was a statistically insignificant difference in XIAP expression between low- and intermediate-grade carcinomas." (PMID 41253834, 2025). "Studies in HCT116 cells, a CRC cell line, showed that ACTIN polymerization and, hence the formation of F-ACTIN, is strictly dependent on the X-linked inhibitor of apoptosis protein (XIAP), a member of the inhibitor of apoptosis (IAP) family, which is over-expressed during the cancer progression." (PMID 39001432, 2024). "Many cancers can escape apoptosis by overexpressing XIAP [–20, –34, –56, 78–84]." (PMID 38684550, 2024). "NAIP, BIRC2/5, and XIAP expression were related to the individual cancer stages of HNSCC." (PMID 38364254, 2024). "Importantly, XIAP overexpression has been correlated to increased malignant transformation, poor prognosis, and decreased response to cancer therapies." (PMID 39695179, 2024). "Therefore, our results provide the foundation for developing a new class of small-molecules that target the unique binding site of ARTS within XIAP, and can be effective against a wide range of cancers." (PMID 38684550, 2024). "The results of these XIAP inhibitors indicate that play an important role in the mechanisms of cancer treatment, whether it is inhibiting cancer cell proliferation or enhancing the sensitivity of chemotherapy drugs." (PMID 38044583, 2024). "This could lead to further individualized cancer treatment with less aggressive therapy protocols for XIAP-positive tumors or more intensive follow-up for XIAP-negative tumors." (PMID 36472768, 2023). "So, the role of XIAP as a driver or suppressor of metastasis may depend on the cancer tissue and cell type." (PMID 37154878, 2023). "Besides, previous work has not only indicated the oncoprotein-like properties of XIAP in cancer, but also revealed its functions in mediating regulation of cell apoptosis in cancer." (PMID 37710286, 2023). "The XIAP protein combines with the E3 ubiquitin ligase to ubiquitinate a range of targets, including caspases, thereby conferring resistance to chemotherapy or radiotherapy mediated by apoptosis suppression in cancer cells." (PMID 37558683, 2023). "Overexpression of XIAP is frequently observed in human cancers and may contribute to tumorigenesis by evading cancer cell apoptosis." (PMID 37154878, 2023).
cancer (continued). "Moreover, MBZ can modulate various cancer-associated pathways, including MAPK14, MEK-ERK, C-MYC, USP5/c-Maf, TNIK, XIAP, ELK/SRF, NFKB, MYC/MAX, E2F/DP1, TGF/SMAD, AP1, and STAT1/2, dependent on the specific cancer model." (PMID 36674870, 2023). "Cu-CQ treatment seems to cause XIAP clearance and this effect was observed only in cancer prostate cells and not in normal prostate epithelial cells, indicating a selective behavior of Cu-CQ." (PMID 35309510, 2022). "STAT1 is also a key player in cancer cell apoptosis and has crosstalk with XiaP." (PMID 35475470, 2022). "Furthermore, XIAP hyperexpression accelerates the tumor growth and induces blockage of apoptosis, leading to the development and progression of cancer." (PMID 35572727, 2022). "In addition, TRIM8 mediates stable XIAP, and prevents the activation of caspase-3, thereby inhibiting cell apoptosis, and promoting cancer." (PMID 36353542, 2022). "We identified an enrichment for BCL2 in immune, and BAK, SMAC, and XIAP in cancer cells." (PMID 34754079, 2022). "Thus, more attention has thus far been focused on XIAP suppression for developing new strategies to prevent and/or treat cancer." (PMID 36142326, 2022). "XIAP modulation is becoming an important target for cancer therapy, in fact, it may confer therapeutic resistance and may modulate signaling factors involved in other processes, such as necroptosis, autophagy and immunosuppression." (PMID 35736153, 2022). "It is noted that the overexpression of XIAP promotes the survival of cancer cells and the development of cancer; however, mitochondria, in this case, may have a protective function." (PMID 35203638, 2022). "This heptapeptide could induce apoptosis of cancer cells, probably due to its interaction with XIAP, which liberates caspase-9 from the inhibitory complex with XIAP and facilitates its activation." (PMID 36360120, 2022). "XiaP protects cells from apoptosis, thereby contributing to cancer development." (PMID 35475470, 2022). "In accordance with the assumption that HTDT-6-2-3-2 could induce apoptosis in cancer cells, XIAP was predicted to be at the top of a list of potential targets for HTDT-6-2-3-2." (PMID 36360120, 2022). "The inhibition of the BIR3 domain of XIAP by small molecules has been considered an emerging therapeutic target in the discovery of new anti-cancer therapeutics based on promoting apoptosis in cancer cells." (PMID 36615253, 2022). "Additionally, trichothecin-induced apoptosis downregulates the expression of Survivin, XIAP, Bcl-xL, Bcl-2, and cyclin D1 via abrogation of NF-κB activation in human cancer cells featuring constitutively active NF-κB." (PMID 35955813, 2022). "Overexpression of inhibitors of apoptosis proteins (IAPs) such as X-linked IAP (XIAP) and cellular IAP (cIAP) 1/2 is one mechanism that can promote cancer cell survival since they inhibit caspases and block formation of protein complexes that stimulate pro-apoptotic signaling." (PMID 36286042, 2022). "The X-linked inhibitor of apoptosis protein (XIAP) is considered the most potent inhibitor of cell death, and it is well established that XIAP promotes resistance to chemotherapy, radiation, and anti-cancer immune responses." (PMID 34199946, 2021). "The compound 18 inhibited XIAP (X-linked inhibitor of apoptosis protein) expression, and due to caspases 3 and 7 activation and cleavage of PARP (Poly ADP-ribose polymerase), induced apoptotic cell death in cancer cells." (PMID 34299599, 2021). "In addition, XIAP expression can interfere with the effect of gemcitabine in PC cells, as knocking down XIAP levels in PC cells resensitizes cancer cells to gemcitabine." (PMID 33669111, 2021). "Furthermore, the expression of IAP family members, such as c-IAP1, c-IAP2, survivin, XIAP and livin, and Bcl-2 family members, such as Bcl-2, Mcl-1, Bak, and Bad, which play critical roles in cancer cells apoptosis regulation, was examined by western blotting." (PMID 34926237, 2021).